ABCB1 (ATP binding cassette subfamily B member 1)
Diseases named in the same sentence as ABCB1 in open-access papers (continued):
Sharing a sentence is not in itself a finding about the gene and the disease.
cancer (continued). "P-glycoprotein (P-gp/ABCB1/MDR1) belongs to the ATP-binding cassette (ABC) transporter superfamily, which actively exports structurally and functionally unrelated chemotherapeutic drugs from cancer cells to the extracellular space." (PMID 33974673, 2021). "The potential partners of 4SC-202 in combination therapy should favor agents that target autophagenesis, which promotes cancer cell survival, CSC signaling pathways such as Wnt and Notch, drug-resistant genes such as ABCB1, key components of the proteasome, and immune cells for immunotherapy." (PMID 34439353, 2021). "ABCC1 and ABCB1 transporters conferred resistance to multidrug resistance (MDR), an intrinsic or acquired cross-resistance toward different chemotherapeutic drugs, which has been considered as one of the primary reasons for the failure in cancer chemotherapy." (PMID 34933679, 2021). "Using Tariquidar (a potent ABCB1-antagonist) has been tested in combination with carboplatin/paclitaxel in phase III trials in NSCLC patients, based on the presumption that the inhibitor is going to increase the effect of cancer therapy." (PMID 34065402, 2021). "While various mechanisms are responsible for resistance of cancer cells to cytotoxic drugs, overexpression of ABC efflux proteins (e.g., P-gp/ABCB1, BCRP/ABCG2 and MRP/ABCC1) on the tumor cell membrane play a significant role in the emergence of resistance to antineoplastic drugs." (PMID 33918289, 2021). "To date, there remains no standard of care for patients whose tumors harbor ABCB1 fusion-mediated drug-resistant cancer cells." (PMID 34830797, 2021). "However, the effect of prolonged citarinostat exposure on the protein expression of ABCB1 and ABCG2 in cancer cells remains to be determined." (PMID 33807514, 2021). "We found that the reduced intracellular accumulation of citarinostat in KB-V-1 and S1-M1-80 cancer cells was significantly restored by tariquidar and Ko143, signifying that the activity of ABCB1 and ABCG2 contributes greatly to the reduced efficacy of citarinostat in these cancer cells." (PMID 33807514, 2021). "Mechanism studies indicated that NVP-CGM097 could reverse ABCB1-mediated MDR by directly blocking the ABCB1-mediated drug efflux and raising the accumulation of chemotherapeutic drugs in cancer cells." (PMID 32793491, 2020). "Additionally, there is a need to expand these studies from the usual ABCB1, ABCC1, and ABCG2, to encompass all the other transporters identified as dysregulated in cancer." (PMID 32587767, 2020). "We found that sitravatinib blocks the drug efflux function of ABCB1 and ABCG2 in a concentration-dependent manner but does not significantly alter the protein expression of ABCB1 or ABCG2 in multidrug-resistant cancer cells." (PMID 31941029, 2020). "Since drug-selected cancer cells may develop MDR due to multiple mechanisms, the drug resistance mechanism in HEK293/ABCB1 is only via overexpression of ABCB1 transporter." (PMID 33519482, 2020). "Several reports have demonstrated that in addition to inhibiting the drug efflux function of ABCB1 and ABCG2, the transient down-regulation of these transporters is one of the common alternative mechanisms in which the multidrug-resistant cancer cells can be re-sensitized to chemotherapy." (PMID 31941029, 2020). "To establish wider evidence for a relationship between ABCB1 expression level and ICEC0942 response, we examined the correlation between mRNA levels of ABCB1 and ICEC0942 GI50 in a panel of 854 cancer cell lines representing a variety of cancer types." (PMID 31530935, 2020). "[18F]AVT-011 PET measures ABCB1 function in tumors expressing clinically relevant levels of ABCB1 and could potentially be used to detect MDR in select human cancers." (PMID 31729540, 2020). "Notably, previous studies have reported that certain TKIs can reverse multidrug resistance mediated by ABCB1 and ABCG2 in cancer cells by interacting strongly with these ABC drug transporters." (PMID 31941029, 2020).
cancer (continued). "Since our cell proliferation studies confirmed that EC16-1/saporin is a cytotoxic compound in the cancer cell types used in the study, we subsequently determined the effect of EC16-1/saporin on the induction of apoptosis in the parental and ABCB1- and ABCG2-overexpressing cells." (PMID 32098067, 2020). "Among them, ABCB1, ABCG2, and ABCCs have been widely reported as MDR inducers in cancer cells." (PMID 33364237, 2020). "In conclusion, this study elucidated that the reversal mechanism of RN486 to ABCB1-mediated MDR is to inhibit anti-cancer drugs being pumped out by ABCB1 transporter without obstructing the expression and subcellular localization of ABCB1 protein." (PMID 32984343, 2020). "Interestingly, like nilotinib, sitravatinib is also a TKI that re-sensitizes ABCB1- and ABCG2-overexpressing cancer cells to chemotherapeutic drugs by modulating the drug efflux function of both drug transporters." (PMID 31941029, 2020). "In conclusion, our study demonstrated that as an anti-cancer drug approved by FDA, erdafitinib could antagonize ABCB1-mediated MDR." (PMID 32670878, 2020). "The cytotoxic activity of ERK5-IN-1 were evaluated in vitro using a panel of cancer cell lines stabling expressing ABCB1 or ABCG2 and ERK5-IN-1 at non-toxic concentrations up to 0.4 μM were used for reversal assay in vitro." (PMID 32164732, 2020). "Furthermore, we confirmed that the Ras/MEK-RSK-ABCB1 and Ras/MEK-HIF-1α-FECH axes are involved in the regulation of PpIX accumulation in human cancers, as inhibition of RSK, HIF-1α, or ABCB1 increased PpIX accumulation in multiple human cancer cell lines." (PMID 33335181, 2020). "The increase in PpIX accumulation by inhibiting RSKs, HIF-1α, or ABCB1 in the human cancer cell lines was not as robust as that by inhibiting MEK." (PMID 33335181, 2020). "Consequently, ABCB1 and ABCG2 remain a crucial therapeutic target for improving therapeutic outcomes in cancer patients undergoing chemotherapy." (PMID 31941029, 2020). "In addition, EC16-1/saporin induced apoptosis in parental and ABCB1- and ABCG2-overexpressing cancer cells." (PMID 32098067, 2020). "Previous reports have demonstrated that ABCB1 and ABCG2 are capable of effluxing small molecule inhibitors of receptor tyrosine kinases (RTKs) such as sunitinib and imatinib out of cancer cells." (PMID 32466597, 2020). "In this study, we explored whether RN486, another BTK inhibitor, was competent to surmount ABCB1-mediated MDR and promote relevant cancer chemotherapy." (PMID 32984343, 2020). "Our data suggest that erdafitinib reverses multidrug resistance by inhibiting the drug transport function of ABCB1, and not by downregulating the ABCB1 protein in ABCB1-overexpressing cancer cell lines." (PMID 32466597, 2020). "Therefore, in this study, we determined the efficacy of MCA in ABCB1- and ABCG2-overexpressing cancer cells and in HEK293 cells transfected with either ABCB1 or ABCG2 cDNA." (PMID 32676451, 2020). "Our findings suggest that the EC16-1/saporin combination could potentially be a novel therapeutic treatment in patients with parental or ABCB1- and ABCG2-positive drug-resistant cancers." (PMID 32098067, 2020). "In particular, the expression of ATP-binding cassette subfamily B member 1 (ABCB1), an ATP-dependent drug efflux pump mediating the extrusion of chemotherapy drugs outside the cytoplasm of cancer cells in the extracellular microenvironment, is regulated by β-catenin/TCF/LEF-binding sites in BC." (PMID 33260642, 2020). "As the MDR in drug-selected cancer cells might be multifactorial, the transfected ABCB1-overexpressing cell line (HEK293/ABCB1) was used to verify the actual role of ABCB1 and similar reversal effects were observed." (PMID 32707710, 2020). "The group expressing ABCB1 had a significantly higher incidence of vessel invasion and lymph metastasis (P < 0.001) than the group that had carcinoma with no detectable ABCB1 expression (P < 0.01), a pointer to the propensity of ABCB1+ve cells for metastasis." (PMID 32587767, 2020).
cancer (continued). "The inhibitory effect of TMP195 on ABCB1- and ABCG2-mediated drug transport, as well as its effect on the protein expression of ABCB1 and ABCG2 in multidrug-resistant cancer cells were examined to elucidate the potential mechanism(s) of chemosensitization by TMP195." (PMID 31905792, 2019). "ABCB1 and ABCG2 when overexpressed, transport chemotherapeutic drugs out of cancer cell." (PMID 31570733, 2019). "For example, multidrug resistance protein 1 (MDR 1), also known as P-glycoprotein (P-gp) and ABCB1, is a member of the ATP-binding cassette (ABC) transporter protein family, which is overexpressed in many types of cancer cells." (PMID 34137971, 2019). "Although P-gp’s efflux function was inhibited, the ABCB1 mRNA levels were not significantly influenced by these triterpenoids under 72 h treatment, unlike in P-gp over-expressing cell line (ABCB1/Flp-InTM-293) or MDR cancer cell line (KB/VIN)." (PMID 31766413, 2019). "Drug-resistance of cancer cells may be a result of the overexpression of multispecific transporters of the ATP-binding cassette superfamily (ABC transporters), such as ABCB1 (P-glycoprotein)." (PMID 30813251, 2019). "In terms of MDR reversal effects, ZA-A exhibited the best cytotoxicity-enhancing ability, sensitizing the P-gp over-expressing cell line (ABCB1/Flp-InTM-293) and MDR cancer cell line (KB/VIN) toward several chemotherapeutic drugs, such as doxorubicin, paclitaxel and vincristine." (PMID 31766413, 2019). "We then demonstrated that TMP195 enhances drug-induced apoptosis of multidrug-resistant cancer cells by modulating the drug transport function of ABCB1 and ABCG2, without affecting the protein expression of either transporter." (PMID 31905792, 2019). "ABCB1 knockout mice are not cancer-prone in the laboratory conditions where is free from genotoxic substances but are more sensitive to toxins than wild-type mice." (PMID 31249297, 2019). "The combination of VS-4718 with substrate drugs of ABCB1 and ABCG2 transporters might be used for cancer clinical treatment to elude MDR if it could be validated in in vivo models." (PMID 30425643, 2018). "Our study provides a clue that the combination of VS-4718 with ABCB1 or ABCG2 substrate-drugs, like doxorubicin or topotecan, as well as SN-38, could be a novel treatment strategy to antagonize resistance in cancer patients." (PMID 30425643, 2018). "Furthermore, reduced ATPase activity, mRNA transcription, and protein expression levels of ABCB1 and ABCG2 were observed in a concentration dependent manner in MDR cancer cells." (PMID 30544754, 2018). "ABCB1 and ABCG2, which are important ATP-binding cassette (ABC) transporters, contribute to multidrug resistance in tumor chemotherapy through transporting anti-tumor drugs to the outside of cancer cells." (PMID 28438180, 2017). "Further studies will be needed to investigate whether our findings in this study can be translated to other cancers in which MUC1 and ABCB1 are positive." (PMID 28796259, 2017). "It is well established that the overexpression of p-glycoprotein (P-gp or ABCB1) and breast cancer resistance protein (BCRP or ABCG2) play a major role in mediating MDR in certain types of cancer cells." (PMID 28824426, 2017). "Our data collectively support a model in which MUC1 induces acquired chemotherapy resistance by upregulating ABCB1 in an EGFR-dependent manner, providing a novel molecular basis of using the EGFR inhibitor in MUC1-positive cancers to prevent chemotherapy resistance." (PMID 28796259, 2017). "Numerous reports show that in most cancer cases that do not respond to therapy, an abundant expression of ABCB1, ABCC1, or ABCG2 appears as poor prognostic factor." (PMID 28623509, 2017). "Among them, P-glycoprotein (P-gp/ABCB1), multidrug-resistant protein 1 (MRP1/ABCC1), breast cancer resistant protein (BCRP/ABCG2/MXR/ABCP), and multidrug-resistant protein 10 (ABCC10/MRP7) transporters frequently drive chemosensitive cancers to MDR." (PMID 28646911, 2017).
cancer (continued). "Thus, we determined the promoter methylation patterns of ABCB1, ABCC1 and ABCG2 in 19 human cancer cell lines." (PMID 27689338, 2016). "However, only three major ABC drug transporters, including P-glycoprotein (P-gp; ABCB1), multidrug resistance protein 1 (MRP1; ABCC1) and ABCG2 (BCRP; MXR), are believed to seriously affect cancer chemotherapy." (PMID 26959063, 2016). "The correlation of point mutations in class III β-tubulin (TUBB3) and the prominent overexpression of ATP-binding cassette P-glycoprotein (ABCB1), a multidrug resistance gene, have been protruding mechanisms of resistance to microtubule disruptors such as paclitaxel (PTX) for many cancers." (PMID 27284014, 2016). "Since many cancer cells may develop MDR via different types of ABC transporters, we examined ABCB1, ABCG2, ABCC1, and ABCC10 in this study." (PMID 27649127, 2016). "Among them, ABCB1, ABCC1, and ABCG2 play major roles in the development of MDR in cancer cells." (PMID 26506420, 2015). "Of note, ABCB1 (also known as MDR1 or P-gp) was found highly up-regulated in our study, which is known to be a key player in mediating multidrug resistance (MDR) in cancer." (PMID 25818003, 2015). "Trametinib significantly potentiated the effects of two ABCB1 substrates vincristine and doxorubicin on inhibition of growth, arrest of cell cycle and induction of apoptosis in cancer cells overexpressed ABCB1, but not ABCC1 and ABCG2." (PMID 25915534, 2015). "One of the main features of chemoresistant cancer cells is the high cell surface expression of ATP binding cassette (ABC) transporters, such as P-glycoprotein (Pgp/ABCB1), multidrug resistance (MDR) related proteins (MRPs/ABCCs) and breast cancer resistance protein (BCRP/ABCG2)." (PMID 25686827, 2015). "High expressions of ABCG2, ABCB1, or ABCC1 were validated in CSCs in various cancers, and the ability of CSCs to extrude Hochest 33342 by ABCG2 was used to develop the “side population” method, which is frequently used to isolate stem-like cells from primary tumors or cancer cell lines." (PMID 26431273, 2015). "It was also discovered that both miR-451 and miR-27a could regulate ABCB1 expression in multidrug resistant A2780DX5 and KB-V1 cancer cell lines." (PMID 26649310, 2015). "Moreover, ABCB1 and ABCG2 are frequently found highly expressed on cancer cells playing an important role in cancer cell chemoresistance." (PMID 25749379, 2015). "Therefore, discovery of a novel lead compound as ABCB1 inhibitor is still urgent and promising for overcoming MDR in cancer chemotherapy." (PMID 26296969, 2015). "IGF2BP3 may increase the cancer stem cell percentage through IGF2 in HCC, which probably lead to the stemness-related genes like CD133 and ABCB1 expression up-regulation." (PMID 26327240, 2015). "In the present study, we showed that trametinib significantly potentiated the effects of vincristine and doxorubicin on inhibition of growth, arrest of cell cycle and induction of apoptosis in cancer cells overexpressed ABCB1, but not ABCC1 and ABCG2." (PMID 25915534, 2015). "For example, HAX1, RNF2, and CAV1 interact with ABCB1, and these proteins are also prioritized in the top 5 candidate list in VCR study using ProteinRank and involved in chemoresistance in various carcinoma cells." (PMID 26039373, 2015). "The efflux transporters, including P-glycoprotein (ABCB-1/P-gp), multidrug resistance proteins (MRPs), and breast cancer resistance protein (BCRP) are over-expressed in many cancer cells, limiting the entry of the drug into the inside of cells and conferring the resistance of cells to the drugs." (PMID 25372840, 2014). "Although such heterogeneity has been described previously, ABCG2- and ABCB1-expressing cancer cells have never been systematically compared on the functional level." (PMID 25216521, 2014).
cancer (continued). "Among ABC transporter family, three of them, ABCB1 (P-glycoprotein/Pgp), ABCC1 (multidrug resistance protein 1/MRP1) and ABCG2 (breast cancer resistance protein /MXR/BCRP) appear to play an important role in the development of MDR in cancer cells." (PMID 24653706, 2014). "The in vivo studies further confirmed the reversal effect of lapatinib on ABCB1-mediated MDR, therefore indicated that combination of lapatinib with other anticancer drugs may be important in surmounting clinical resistance in cancer chemotherapy." (PMID 25268163, 2014). "We hypothesized that afatinib can effectively compete with chemotherapeutic agents for binding with ABCB1, ABCC1, or ABCG2 and thus increase drug concentrations in resistant cancer cells." (PMID 25436978, 2014). "Studies with ABC transporter-overexpressing carcinoma cell models confirmed that nilotinib effectively reversed ABCB1- and ABCG2-mediated drug resistance, while showed no significant reversal effect on ABCC1- and ABCC4-mediated drug resistance." (PMID 24651611, 2014). "Comparing tumor and normal tissues, three of the five analyzed genes showed a significant lower expression in tumors than in healthy control tissues (ABCB1, p<0.0001; ABCC2, p<0.005; ABCG2, p<0.0001), whereas ABCC1 expression was significantly up-regulated in the carcinomas (p<0.0001)." (PMID 25275603, 2014). "Three ABC transporters, including P-glycoprotein (P-gp, MDR1, ABCB1), multidrug resistance protein 1 (MRP1, ABCC1), and breast cancer resistance protein (BCRP, MXR, ABCG2), play important roles in most cases of MDR in cancer cells." (PMID 24391798, 2013). "Although intestinal ABCB1 transport activity can be determined using a model substrate, this has not been done on cancer cells or cancerous tissue." (PMID 23977225, 2013). "ABCB1 (also known as P-glycoprotein/P-gp), ABCC (also known as multidrug resistance protein/MRP) subfamily and ABCG2 (also known as breast cancer resistance protein/BCRP) are considered major players in the development of MDR in cancer cells." (PMID 24069321, 2013). "Studies have shown that both the multidrug transporter ATP Binding Cassette, sub-family B, member 1 (ABCB1, MDR1) and the ATP Binding Cassette, sub-family C, member 1 (ABCC1, MRP1) play a role in enhancing the cellular efflux of anti-cancer drugs, including paclitaxel." (PMID 22179563, 2012). "Despite some recent findings demonstrating that TCF consensus sites for β-catenin were functional in the ABCB1 promoter in other types of cancer, in CML, this regulation has not yet been investigated." (PMID 22823957, 2012). "Overall, these experiments suggest that neither vardenafil nor tadalafil inhibit the expression of the ABCB1 transporter and they do not alter the translocation of ABCB1 in MDR cancer cells." (PMID 21552528, 2011). "Importantly, QB1561 showed lower IC50 values in parent cancer cell lines with minimal ABC transporter expression compared to resistant cells, suggesting that it may be a weak substrate of ABCB1 or ABCG2." (PMID 40066335, 2025). "The transient resistance of cancer cells to the drug oxaliplatin is the result of drug-induced upregulation of the BLACAT1 lncRNA that, in turn, serves as an inhibitory sponge (ceRNA) of miR-136 leading to elevated expression of ABCB1 and export of the drug from the cancer cells." (PMID 39761690, 2025). "Interestingly, for six genes (KISS1, CXCR4, PSMB9, ABCB1, FGF2, and IL6) found to be up-regulated along with GCS, their overexpression pursuant to platinum-agent treatments in patients promoted resistance to those same agents in cancers." (PMID 40507922, 2025).